ASXL3 (ASXL transcriptional regulator 3)
Diseases named in the same sentence as ASXL3 in open-access papers:
ASXL3 is named in the same sentence as 48 diseases in open-access papers, as found by Europe PMC text mining. Sharing a sentence is not in itself a finding about the gene and the disease. The quoted sentences say what the papers report.
Bainbridge-Ropers syndrome (16 papers, 2015 to 2026). "Mutation of the third transcription factor from this gene (ASXL-3) is responsible for the clinical condition of Bainbridge-Ropers syndrome (BRPS)." (PMID 42111080, 2026). "Bainbridge-Ropers syndrome (BRS) is a neurodevelopmental disorder predominantly caused by pathogenic variants in the ASXL3 gene, which have been conventionally considered to occur de novo." (PMID 40980137, 2025). "The ASXL gene family also includes ASXL2 and ASXL3, and variants in these genes are implicated in Shashi-Pena and Bainbridge-Ropers syndromes, respectively." (PMID 35361921, 2022). "Bainbridge-Ropers syndrome (BRPS) is caused by monoallelic ASXL3 variants on chromosome 18 first reported in 2013." (PMID 35172777, 2022). "Bainbridge-Ropers syndrome (BRPS) or additional sex combs-like 3 (ASXL3)-related disorder is a neurodevelopmental disorder caused by a de novo missense mutation in the ASXL3 gene found on chromosome 18." (PMID 36699804, 2022). "Bainbridge-Ropers syndrome resulting from ASXL3 gene mutations also includes features of autism spectrum disorder." (PMID 32132929, 2020). "De novo sequence variants, including truncating and splicing variants, in the additional sex-combs like 3 gene (ASXL3) have been described as the cause of Bainbridge-Ropers syndrome (BRS)." (PMID 31180560, 2019). "Bainbridge-Ropers syndrome is caused by monoallelic ASXL3 variants on chromosome 18." (PMID 35172777, 2022). "Based on the preclinical studies on the loss of ASXL3 function, it can be inferred that the global genomic aberration patterns of these loci may lead to the early-onset and global developmental failure characteristics of Bainbridge-Ropers syndrome." (PMID 41458212, 2025). "Indeed, germ-line de novo truncating variants in human ASXL1, ASXL2, and ASXL3 cause the congenital and developmental disorders Bohring-Opitz, Shashi-Pena, and Bainbridge-Ropers syndromes, respectively, and somatic mutations of ASXL1, ASXL2, and ASXL3 occur in solid and hematologic malignancies." (PMID 36068610, 2022). "Background/Objectives: Bainbridge-Ropers syndrome (BRPS) is a rare neurodevelopmental disorder caused by truncating and splicing pathogenic variants in the additional sex combs-like 3 (ASXL3) gene." (PMID 42194125, 2026). "This study conducted direct qualitative and quantitative phenotyping in 15 individuals with Bohring-Opitz Syndrome (BOS- ASXL1) and Bainbridge-Ropers Syndrome (BRS- ASXL3)." (PMID 38027485, 2023). "The characteristics of ASXL3-related syndrome (also called Bainbridge-Ropers syndrome) are DD/ID (moderate to severe), language impairment or absent speech, hypotonia and dysmorphic facial features." (PMID 37007974, 2023). "Two specific CMDs discussed here include Bohring-Opitz Syndrome (BOS), caused by truncating variants in ASXL1, and Bainbridge-Ropers Syndrome (BRS), caused by truncating variants in ASXL3." (PMID 38027485, 2023). "Here, we present developmental phenotyping data on individuals with Bohring-Optiz Syndrome (BOS – ASXL1) and Bainbridge-Ropers Syndrome (BRS – ASXL3) related disorders, two CMDs highly penetrant for motor and developmental delays." (PMID 38027485, 2023). "More recently, germline pathogenic variants in ASXL2 (reported in 2016) and ASXL3 (reported in 2013) were identified as the causes for Shashi-Pena syndrome (SHAPNS; MIM# 617190]) and Bainbridge-Ropers syndrome (BRS; MIM# 615485), respectively." (PMID 35361921, 2022). "We have found that ASXL3 protein knockdown during early embryo development highly perturbs neural cell fate specification, potentially resembling the Bainbridge-Ropers syndrome phenotype in humans." (PMID 32132929, 2020). "This patient has a mutation in ASXL3, which is associated with the newly recognized Bainbridge-Ropers syndrome that would not have been identified by conventional genetic testing because it was not available at the time of diagnosis." (PMID 26284228, 2015).
small cell lung carcinoma (9 papers, 2020 to 2025). Small cell lung cancer (SCLC) is a highly aggressive malignant neoplasm, accounting for 10-15% of lung cancer cases, characterized byrapid growth, and early metastasis. "For instance, previous reports showed that ASXL3 acts as a novel pluripotency factor in respiratory epithelial cells associated with small cell lung cancer." (PMID 34559584, 2021). "The additional sex combs-like 3 (ASXL3) gene, is a protein associated with the polycomb repressive complex 2 and is upregulated in small cell lung cancer cells." (PMID 34559584, 2021). "Moreover, we have recently characterized a human small cell lung cancer (SCLC)-specific epigenetic axis comprised of BAP1/ASXL3/BRD4." (PMID 36180891, 2022). "Furthermore, ASXL3 was found to serve as an effective biomarker for predicting the sensitivity towards BET protein inhibitors in small cell lung cancer (SCLC), highlighting its potential as an actionable biomarker." (PMID 34646089, 2021). "A study demonstrated that ASXL3 forms an oncogenic axis with BRD4 and BAP1, activating ASCL1/MYCL/E2F signaling in small cell lung cancer." (PMID 38791157, 2024). "Genome-wide CRISPR-Cas9 dropout screen in small cell lung cancer (SCLC) cells identified PAX9 as an essential factor that is overexpressed and is transcriptionally driven by the BAP1/ASXL3/BRD4 epigenetic axis." (PMID 35628401, 2022). "Intriguingly, ASXL3, similar to ASXL1 and ASXL2, forms a PR-DUB complex with BAP1 but also exclusively interacts with BRD4, which binds to acetylated histones via its bromodomains in small cell lung carcinoma." (PMID 38791157, 2024). "In addition, the ET domain–binding motif, which shares similar amino acid sequences from other BRD4-ET–binding proteins such as CHD4 and NSD2/3, also mediates interaction of BRD4-ET with ASXL3 and functionally links BRD4 to the BAP1 complex in a small-cell lung cancer (SCLC) subtype." (PMID 34540900, 2021). "In small cell lung cancer patients, BRD4 interacts with ASXL3 but not ASXL1 or ASXL2." (PMID 38791157, 2024).
Intellectual disability (7 papers, 2014 to 2025). "ASXL3 was identified using this methodology, and pathogenic variants of ASXL3 are among the top 10 single-gene causes of developmental delay and intellectual disability." (PMID 39610869, 2024). "De novo truncating and splicing pathogenic variants in the Additional Sex Combs‐Like 3 (ASXL3) gene are known to cause neurodevelopmental delay, intellectual disability, behavioral difficulties, hypotonia, feeding problems and characteristic facial features." (PMID 36177608, 2023). "In a WES study performed aiming to uncover the susceptibility genes contributing to ASD, a mutation was found in the ASXL3 gene in ASD patients with intellectual disability." (PMID 35205231, 2022). "For instance, certain nonsense mutations in ASXL3 are associated with syndromic intellectual disability, but other nonsense variants near the 3′ terminus are apparently neutral variants." (PMID 24162188, 2014).
developmental delay (5 papers, 2013 to 2024). "Eleven children had de novo SNVs, 2 of whom had de novo ASXL3 variants with mild global developmental delay (DD) and minor dysmorphic facial features besides autistic symptoms." (PMID 37007974, 2023). "In summary, we describe the use of familial exome sequencing to discover a de novo framshift mutation in the ASXL3 gene in a patient with feeding difficulties, microcephaly, severe global developmental delay, and craniofacial anomalies." (PMID 24044690, 2013). "We provide additional evidence that, truncating and frameshifting mutations in the ASXL3 gene are the cause of a newly recognized disorder characterized by severe global developmental delay, short stature, microcephaly, and craniofacial anomalies." (PMID 24044690, 2013). "In the present study, a novel de novo frameshift variant in the ASXL3 gene, which could lead to a truncated protein in a young patient with severe psychomotor developmental delays and microcephaly, was detected." (PMID 31180560, 2019). "Although most ASXL3-related syndromes rely on molecular confirmation, many individuals with pathogenic variants of ASXL3 can be identified by a combination of clinical symptoms and unique phenotypes and do not omit those with mild developmental delays." (PMID 37007974, 2023). "However, they had only mild developmental delay with IQ/DQ higher than 55, and no obvious signs of hypotonia or epilepsy compared with other patients with ASXL3 variants." (PMID 37007974, 2023).
Bohring-Opitz syndrome (4 papers, 2013 to 2023). "Heterozygous de novo truncating variants in ASXL3 have recently been reported in 4 patients with a novel clinical phenotype similar to Bohring-Opitz syndrome, and are consistent with this patient’s clinical findings." (PMID 24044690, 2013). "We have identified truncating mutations in ASXL3 as the likely cause of a novel syndrome with phenotypic overlap with Bohring-Opitz syndrome." (PMID 23383720, 2013). "Here we describe an apparently novel syndrome, likely caused by de novo truncating mutations in ASXL3, which shares characteristics with Bohring-Opitz syndrome, a disease associated with de novo truncating mutations in ASXL1." (PMID 23383720, 2013). "They found that some patients with clinical manifestations resembling those of Bohring-Opitz syndrome (BOS), which is associated with de novo truncating or missense mutations in the ASXL1 gene, actually had abnormalities in the ASXL3 gene rather than ASXL1 mutations." (PMID 36699804, 2022).
autism spectrum disorder (3 papers, 2020 to 2021). A spectrum of developmental disorders that includes autism, and Asperger syndrome. "De novo truncating mutations in Additional sex combs-like 3 (ASXL3) have emerged as the cause of BRS, while missense mutations in ASXL3 have been identified in individuals with autism spectrum disorder (ASD)." (PMID 32132929, 2020). "BRPS is caused by de novo dominant truncating variants in the transcriptional regulator gene Additional Sex Combs Like 3 (ASXL3), and missense variants in ASXL3 have been identified in individuals with autism spectrum disorder (ASD)." (PMID 32517662, 2020). "The ASXL3 gene is differentially expressed in human neural stem cells treated with dihydrotestosterone, indicating ASXL3 association with neurodevelopmental disorders including autism spectrum disorder." (PMID 34559584, 2021). "Human genomic studies also identified missense ASXL3 variants associated with autism spectrum disorder, but lacking more severe Bainbridge-Ropers syndromic features." (PMID 32132929, 2020).
lung carcinoma (3 papers, 2018 to 2021). "ASXL3, the polycomb group (PcG) protein, is essential for neuroendocrine (NE) lung cancer development and was shown via KEGG analysis to be associated with the multiple neuron differentiation signaling pathways." (PMID 34646089, 2021). "Thus, ASXL3-high SCLC cells might have a similar feature as ASCL1-high SCLC cells, such as being essential for neuroendocrine (NE) lung cancer development." (PMID 32669118, 2020).
congenital heart disease (2 papers, 2021). A heart disease that is present at birth. "For example, pathogenic CH variants in the ASXL3 gene can lead to a disruption in ASXL3 protein expression, potentially contributing to the development of congenital heart disease." (PMID 33828584, 2021). "Our previous investigations characterized the compound heterozygous mutations (c.2168 C > G*c.5449 C > G) of the ASXL3 gene from a Chinese family of congenital heart disease." (PMID 34559584, 2021). "Our previous study identified compound heterozygous mutations in the ASXL3 gene in a Chinese family presenting congenital heart disease." (PMID 34559584, 2021).
melanoma (2 papers, 2014 to 2022). A malignant, usually aggressive tumor composed of atypical, neoplastic melanocytes. "Our in silico significance and proximity analysis of 28 paired cases (13 WGS and 15 targeted cases) identified known (e.g., BRAF, NRAS, CDKN2A, and GRIN2A) and novel (e.g., EPHA3, GRIN2B, and ASXL3) genes involved in melanoma." (PMID 25393105, 2014).
Emotional lability (1 paper, 2024). Unstable emotional experiences and frequent mood changes; emotions that are easily aroused, intense, and/or disproportionate to events and circumstances. "A 14-year-old Japanese girl with ASXL3-related syndrome was referred to our hospital because of emotional lability lasting for approximately 3 months." (PMID 38711055, 2024). "A 14-year-old girl with ASXL3-related syndrome was referred to our hospital with subacute onset of emotional lability." (PMID 38711055, 2024).
hearing loss (1 paper, 2024). "Meanwhile, FOXP1 was only detected in DD/ID with malformation group, and ASXL3 was most frequently involved in DD/ID with hearing loss group." (PMID 38649797, 2024).
Hirsutism (1 paper, 2024). Abnormally increased hair growth referring to a male pattern of body hair (androgenic hair). "In family HOU4131, previous analyses revealed a pathogenic variant in ASXL3 (HGNC:29357) in both siblings with spasticity, increased deep tendon reflexes, hirsutism, ID, and neuromotor delay who were born into a family reported with an unknown degree of consanguinity." (PMID 38622594, 2024).
neurodevelopmental disability (1 paper, 2025). "Because both ASXL3 andSTXBP1 can lead to neurodevelopmental disability, thisindividual was excluded from further analysis." (PMID 40182320, 2025).
parathyroid adenomas (1 paper, 2025). "It is reported that mutations in ASXL3 gene are associated with sporadic primary hyperparathyroidism and recurrently mutated in sporadic parathyroid adenomas." (PMID 40943102, 2025).
T-cell acute leukemia (1 paper, 2012). "In recent genome sequencing studies rare mutations in ASXL1 and ASXL3 have also been found in chronic lymphocytic leukemia but not in T-cell acute leukemia." (PMID 22436456, 2012). "Mutations in ASXL2 and ASXL3 have not been found in myeloid diseases so far, but ASXL2-MYST3 and EPC1-ASXL2 fusions have been identified in myelodysplastic syndrome and T-cell acute leukemia, respectively." (PMID 22436456, 2012).
trigonocephaly (1 paper, 2013). "Unlike the previously reported cases with ASXL3 mutations, our patient had trigonocephaly, thus, the lack of trigoncephaly may not be a useful in differentiating BOS from this newly recognized condition." (PMID 24044690, 2013).
neurodevelopmental disorder (8 papers, 2013 to 2026). A behavioral and cognitive disorder with onset during the developmental period that involves impaired or aberrant development of intellectual, motor, or social functions. "The estimated prevalence of de novo variants of ASXL3 is approximately 1/193 (50/9625), positioning ASXL3 among the top 10 genes associated with neurodevelopmental disorders in terms of de novo variant frequency." (PMID 39610869, 2024). "Loss of ASXL3 function leads to abnormal chromatin states and dysregulation of key gene expression, ultimately causing structural and functional brain defects, which provides a molecular mechanism for neurodevelopmental disorders such as BRS." (PMID 40980137, 2025). "While the exact prevalence of BRPS is unknown, the Deciphering Developmental Disorders study (n = 9,625 ID trios) identified de novo ASXL3 variants in 50 probands (1:193), placing ASXL3 among the top 10 most frequently mutated genes in neurodevelopmental disorders." (PMID 40980137, 2025).
cancer (7 papers, 2015 to 2022). A tumor composed of atypical neoplastic, often pleomorphic cells that invade other tissues. "Recent studies have highlighted important roles for the ASXL3 gene in congenital disorders and cancer through the identification of multiple ASXL3 pathogenic sequence SNVs and indels." (PMID 31180560, 2019). "However, no studies demonstrated the role of ASXL3, TMOD2, and CEP85L in cancer." (PMID 35550610, 2022).
tumor (5 papers, 2014 to 2022). "The mutation allele frequencies of ATM and JAK3 were significantly correlated with the disease stage, and mutated KMT2D, ASXL3 and JAK3 were positively correlated with the metabolic tumor burden of the patients." (PMID 32695399, 2020). "Moreover, we confirmed the establishment of an epigenetic dynamic interplay between the BAP1/ASXL3 complex and the opposing ncPRC1 complex, which could potentially be targeted for developing other therapeutics in order to increase the effectiveness against SCLC tumor progression." (PMID 35194152, 2022).
adenocarcinoma (1 paper, 2021). A common cancer characterized by the presence of malignant glandular cells. "In total, four novel genes, including NPTX1, PCSK1, ASXL3, and TRIM9, were all significantly upregulated in NEPC compared with the adenocarcinoma samples, and these genes were all associated with the neuroactive ligand receptor interaction pathway." (PMID 34646089, 2021).
connective tissue disorder (1 paper, 2023). A disease involving the connective tissue. "As we collate more data on ASXL3‐related disorder, we will understand better the natural history of this disorder to allow meaningful conclusions on need for additional screening and ongoing surveillance for features of a connective tissue disorder." (PMID 36177608, 2023).
neurological disorders (1 paper, 2021). "The identification of many lncRNAs influenced by the ASXL3 mutation in the mouse cerebrum and cerebellum suggests that lncRNA-mediated transcription regulation controls the expression of these genes in neural cells during neurological disorder progression." (PMID 34559584, 2021). "Our work provides novel insights into the roles of the ASXL3 gene and lncRNA-mRNA interactions in brain functions and neurological disorders." (PMID 34559584, 2021). "This study provides novel insights into the roles of the ASXL3 gene and lncRNA–mRNA interactions in brain functions and neurological disorders." (PMID 34559584, 2021).
ASXL3 also shares sentences with these, for which no sentence is quoted: epilepsy (2 papers); microcephaly (2); Neurodevelopmental delay (2); acute myeloid leukemia (1); aneurysm (1); angiosarcoma (1); arachnodactyly (1); autism (1); autoimmune disease (1); Cerebellar atrophy (1); depression (1); diabetes (1); genetic disorder (1); hematologic malignancy (1); intellectual impairment (1); intestinal T-cell lymphoma (1); medulloblastoma (1); metastatic melanoma (1); neuroblastoma (1); primary hyperparathyroidism (1); scoliosis (1); Shashi-Pena syndrome (1); Strabismus (1); thyroid tumours (1); tobacco use disorder (1); Truncal obesity (1).